ALB (albumin)
Diseases named in the same sentence as ALB in open-access papers (continued):
Sharing a sentence is not in itself a finding about the gene and the disease.
Cirrhosis (continued). "Given the fact that low albumin level reflects liver cirrhosis, while an elevated AST level may not be liver specific, the elevated ALT level was selected as a risk factor of cirrhosis (aOR = 1.03, 95% CI:1.01–1.05, P=0.01)." (PMID 32377514, 2020). "Finally, clinical trials have also assessed the efficacy of long-term albumin administration in patients with cirrhosis and ascites, opening up new perspectives for its use in decompensated cirrhosis [7••, 8•, 9•]." (PMID 32837825, 2020). "However, based on current evidence supporting its efficacy in these complications, we believe that the infusion of albumin for cirrhosis with GIB is favorable to improve the in-hospital prognosis in those with high-risk for non-bleeding death." (PMID 32576140, 2020). "Indeed, aged rats with cirrhosis exhibited serious liver damage reflected by the increase in transaminases and the reduction in serum albumin and bile production in comparison with young rats with aCLD." (PMID 31440376, 2019). "And, a recent large-scale study also found that albumin infusion could improve hyponatremia in patients with cirrhosis." (PMID 31596729, 2019). "Elevated ALT levels, elevated AST level, elevated serum bilirubin, and decreased serum albumin might be indicative of advanced liver disease and even cirrhosis." (PMID 31547539, 2019). "Use of albumin therapy is recommended for management of disease complications in cirrhosis." (PMID 30700489, 2019). "The decision-tree methodology allowed for the synthesis of evidence from multiple clinical trials conducted in Europe with albumin and multiple comparators to evaluate the cost-effectiveness of albumin in the treatment of decompensated cirrhosis requiring LVP with SBP or with HRS." (PMID 31278624, 2019). "The aim of this review is to improve our understanding of the effects of albumin use in cirrhosis by reviewing the currently available evidence and quantifying the effectiveness of intravenous albumin therapy to prevent specific cirrhosis complications, SBP and renal dysfunction, and death." (PMID 30700489, 2019). "In conclusion, albumin infusion may be effective for preventing the development of overt HE and improving the severity of overt HE in patients with cirrhosis." (PMID 31596729, 2019). "Therefore, the objective of this analysis is to evaluate the cost-effectiveness of albumin in the treatment of decompensated cirrhosis in Germany, Italy, and Spain." (PMID 31278624, 2019). "Since in cirrhosis, platelet-derived growth factor receptor beta (PDGFRβ) is upregulated in the liver as well as the kidney, this study coupled Y27 to human serum albumin (HSA) substituted with PDGFRβ-recognizing peptides (pPB), and investigated its effect on PTH in cirrhotic rats." (PMID 30783172, 2019). "In addition, the TBIL level was significantly higher, but ALB level was found to be lower in the compensated cirrhosis group than in the control group (all P < .05)." (PMID 30508917, 2018). "Kawaguchi pointed out that BCAAs, particularly leucine, could activate the mTOR signaling cascade and increase ALB synthesis in animal models of cirrhosis." (PMID 30210344, 2018). "The failure to observe any association between elevated admission serum albumin levels ≥4.5 mg/dL and HAKI in patients with cirrhosis could be due to small sample size (Type II error)." (PMID 29927987, 2018). "Sub-group analysis assessed the impact of cirrhosis on lower albumin levels." (PMID 27389416, 2017). "AS the predictive models including C5a, AST, Laminin, Co-IV, Platelet count, Albumin, HBsAg had the highest AUROCs for significant fibrosis and cirrhosis, we choose the two models as the novel C5a-based fibrosis scores in patients chronically infected with HBV." (PMID 27605044, 2017). "Albumin level decreased in case of cirrhosis and had been utilized in Child-Pugh classification." (PMID 29235488, 2017).
Cirrhosis (continued). "Decreased albumin correlated with worse outcomes in our model, which may be the result of decreased albumin marking decreased liver function in cirrhosis patients." (PMID 29069090, 2017). "Third, the inclusion of GGT, HA, albumin, age, and gender might enhance the efficiency of nomogram in predicting cirrhosis compared with APRI, FIB-4 and S index." (PMID 29235488, 2017). "This study of factors independently prognostic of OS in this population found that tumor extent (e.g. tumor size, number of liver lesions, and tumor thromboses), hepatic function (serum total bilirubin concentration and serum albumin level), cirrhosis were independent baseline predictors of OS." (PMID 27387757, 2016). "As cirrhosis became more severe, the fatty acid binding capacity of albumin gradually declined." (PMID 28101103, 2016). "In the early cirrhosis, there is limited compensation for albumin ion binding capacity." (PMID 28101103, 2016). "Notably, the presence of cirrhosis, a larger tumour, multiple lesions, a higher AST, and lower albumin levels were factors that significantly associated with shorter HCC survival." (PMID 27779207, 2016). "On univariate analysis, old age (≧50 years old), initial presence of cirrhosis, high viral load of serum HCV RNA (>6 log titer of HCV RNA IU/mL), low platelet count (<130,000/mm3), and low serum albumin level (<3.0 g/dL) were significant risk factors associated with the development of HCC." (PMID 27656205, 2016). "However, in CHC patients with cirrhosis, AOPPs-albumin correlated inversely with the serum albumin (r = −0.38, P < 0.05)." (PMID 26665009, 2015). "Previous studies have shown that urine albumin could be a potential biomarker of AKI in patients with cirrhosis." (PMID 26042740, 2015). "Finally, in a recent randomized trial of patients with cirrhosis and episodic hepatic encephalopathy, survival at 90 days was 69 % in those who received albumin compared with 40 % of those who received saline." (PMID 26606982, 2015). "For patients with cirrhosis, the serum albumin concentration was low due to decreased protein synthesis, which could result in a reduced protein-tolvaptan binding rate and an increase in free tolvaptan plasma concentration." (PMID 25383228, 2014). "Hyperoncotic albumin has demonstrated a clear benefit in patients with cirrhosis." (PMID 25394836, 2014). "A more recent RCT reported beneficial effects of albumin plus antibiotic on renal and circulatory function in 110 patients with cirrhosis and infections other than spontaneous bacterial peritonitis; treatment with albumin was an independent predictive factor of survival." (PMID 25042164, 2014). "HCC patients with cirrhosis and low levels of serum albumin may develop protein-energy malnutrition (PEM) with increased catabolism." (PMID 23710167, 2013). "As displayed, those factors increasing age, cirrhosis, hepatic encephalopathy and MELD score significantly increased the risk of death, whereas increasing levels of serum albumin, platelets, triglycerides and sodium indicated a significantly decreased the risk of death." (PMID 23755119, 2013). "Although low pretreatment platelet count and albumin level, suggestive of cirrhosis status, were significant on univariate analysis, the significance of cirrhosis in prediction of on-treatment severe thrombocytopenia may be restricted by small sample size." (PMID 22257364, 2012). "The bilirubin and albumin were also quite sensitive for the presence of cirrhosis." (PMID 21507271, 2011). "It is noteworthy that serum albumin is related with all hemodynamic parameters studied suggesting that, apart from peripheral vasodilatation, plasma oncotic pressure reduction remains an important determinant of hyperdynamic circulation in cirrhosis." (PMID 21143998, 2010). "Post-paracentesis albumin reduces circulatory dysfunction and may enhance survival in cirrhosis." (PMID 41827398, 2026).
Cirrhosis (continued). "Moreover, it outperformed other leading HCC risk prediction models, including: aMAP (Age, Male, Albumin–Bilirubin, Platelets), ADRESS-HCC (Age, Diabetes, Race, Etiology, Sex, Severity of cirrhosis), THRI (Toronto Hepatocellular Carcinoma Risk Index), Agile 3+ and Agile 4+ score." (PMID 41514666, 2026). "Additionally, albumin may be preferred in patients who cannot tolerate high volumes of crystalloids, such as those with cirrhosis." (PMID 40699702, 2025). "To evaluate this hypothesis, we conducted this cohort study to assess if using albumin as an adjunctive resuscitation fluid to crystalloids in patients with cirrhosis and septic shock would improve the percentage shock-free time within the first 48 h of ICU admission." (PMID 40386509, 2025). "Additionally, among patients with CLD, we identified alerts for medication used to treat decompensated cirrhosis, including diuretics (spironolactone, furosemide) and albumin for the treatment of ascites and lactulose for the treatment of hepatic encephalopathy." (PMID 41345999, 2025). "This reflects a significant extracellular fluid volume expansion, which, in patients with cirrhosis, may be accumulated primarily as ascites due to splanchnic vasodilatation, higher removal of desaturated albumin, and an increased transvascular escape rate and activated reticuloendothelial system." (PMID 38667480, 2024). "Albumin binds many substances, such as NO, reactive oxygen species (ROS), and proinflammatory cytokines, which may be involved in the pathogenesis of both peripheral arterial vasodilatation and cardiac dysfunction in patients with cirrhosis." (PMID 38892040, 2024). "Interestingly, various studies have shown that increased albumin does not alter the risk of mortality in cirrhosis." (PMID 38961593, 2024). "Consequently, it creates a therapeutic option—human albumin solution infusions may be used to reduce circulating PGE2 levels and thus reduce the risk of infection in patients with acutely decompensated cirrhosis." (PMID 39273468, 2024). "Additionally, it is essential to closely monitor follow-up levels of creatinine, albumin, sodium, and systemic inflammation, as these may serve as significant prognostic indicators for hospital mortality and the progression of HE in cirrhosis patients." (PMID 39226259, 2024). "Timely albumin administration with an antibiotic regimen may shorten the length of stay and lower costs, thereby reducing hospital resource utilization in patients with cirrhosis and spontaneous bacterial peritonitis requiring fluid resuscitation." (PMID 38899040, 2024). "Thus, serum albumin levels can be used to help grade the severity of cirrhosis." (PMID 39335727, 2024). "Prealbumin changes are more sensitive than albumin, and prealbumin can still be synthesized during the decompensated phase of cirrhosis, whether prealbumin can be used as a measurement of malnutrition in cirrhosis remains to be studied." (PMID 39091687, 2024). "Thus, this study indicated that altered isoforms of human albumin could be utilised to ascertain cirrhosis-induced complications." (PMID 38551716, 2024). "Consequently, albumin is considered a potential agent for the treatment of decompensated cirrhosis." (PMID 36908849, 2023). "Reportedly, serum IGF-1 levels are substantially low in a large percentage of patients with compensated cirrhosis despite normal albumin and prealbumin levels; hence, they may be a more sensitive and earlier indicator of impaired liver function than other conventional parameters." (PMID 37554499, 2023). "However, patients with low albumin levels and hepatic cirrhosis still had a poor prognosis." (PMID 37345190, 2023). "On the other hand, VD deficiency may serve as a marker of PBC severity, given the higher prevalence of cirrhosis complications and worse liver function tests, reflected as lower albumin, as well as higher bilirubin and alkaline phosphatase, levels in patients with deficiency." (PMID 35215528, 2022).
Cirrhosis (continued). "Thus, rifaximin reduces serum ammonia levels and may improve circulating albumin structure in patients with cirrhosis." (PMID 36555935, 2022). "However, whether rifaximin can improve the structure of circulating albumin in patients with cirrhosis remains unclear." (PMID 36555935, 2022). "However, evidence on the association between rifaximin therapy and the structure of circulating albumin in patients with cirrhosis is limited, and to our knowledge, this is the first study to investigate the structure of circulating albumin during rifaximin therapy." (PMID 36555935, 2022). "Increased plasma renin activity in decompensated cirrhosis reflects reduced effective blood or extracellular fluid volume, consequent to portal hypertension and mesenteric vasodilation, with reduction described following albumin infusions for large-volume paracentesis and SBP." (PMID 35333783, 2022). "Finally, the large-scale long-term albumin administration in decompensated cirrhosis (ANSWER) trial showed improved outcomes for patients treated with weekly albumin infusions, including a reduction in spontaneous bacterial peritonitis (SBP) and non-SBP infections." (PMID 35333783, 2022). "However, the results of previous studies suggest that rifaximin may have beneficial effects in reducing systematic oxidative stress, at least in part by decreasing oxidized albumin levels in patients with cirrhosis." (PMID 36555935, 2022). "Moreover, supplementation with branched-chain amino acids (BCAA) in cirrhosis nutrition therapy reportedly improves the structure of circulating albumin, i.e., it decreases oxidative albumin levels, and consequently improves mortality rates in patients with cirrhosis." (PMID 36555935, 2022). "However, L-VFA was associated with lower BMI, sarcopenia, lower serum albumin, cirrhosis and was not an independent risk factor for survival al multivariate analysis." (PMID 36568174, 2022). "In addition, there is growing interest in the association between circulating albumin dysfunction and poor clinical outcome in patients with decompensated cirrhosis and whether treating patients with exogenous albumin infusions could improve this." (PMID 35333783, 2022). "However, we did not test whether meld score, MELD sodium or ALBI and APRI have predictive value in patients with cirrhosis because serum albumin and creatinine fluctuated during pregnancy." (PMID 33832453, 2021). "Among the reasons of benefits of albumin in patients with cirrhosis, expander function depending on its known oncotic properties is well known, although it is now irrefutably clear that the immunomodulatory function of albumin turns to be more important during the therapies for liver cirrhosis." (PMID 34571946, 2021). "Both cirrhosis (P=0.004) and albumin (ALB, P=0.02) could predict OS alone." (PMID 35127471, 2021). "Thus, serum albumin levels can be used to gauge the severity of cirrhosis." (PMID 34198972, 2021). "Furthermore, albumin is also used in critically ill patients for circulatory support and has a well-established safety profile; however, the latter indications in patients with cirrhosis are controversially discussed among experts." (PMID 33270161, 2021). "In addition to hyperbilirubinemia, liver failure, even cirrhosis could lead to low affinity between albumin with bilirubin." (PMID 34527681, 2021). "Furthermore, our results reveal that pre-S2 mutant-positive HCC patients displayed significantly lower serum albumin level, and there was a close correlation between low serum albumin level and a high Child–Pugh cirrhosis score (B/C) in HBV-related HCC patients." (PMID 34575311, 2021). "Such practice has been become routine since the supplementation of intravenous human albumin solution was demonstrated to titrate the higher level of prostaglandin PGE2 that is responsible for the macrophage impairment in patients with acutely decompensated cirrhosis." (PMID 35071299, 2021).
Cirrhosis (continued). "Indeed, albumin administration obtained a 38% reduction in 18-month mortality hazard ratio, eased the management of ascites (with a 50% reduction in the need for LVPs and RA diagnosis) and reduced the incidence of major complications of cirrhosis." (PMID 34830508, 2021). "A novel nomogram (score 0–304) was established using age, platelet count, cirrhosis development, and liver stiffness values, which were independently associated with increased HCC risk, along with hepatitis B e antigen positivity and serum albumin and total bilirubin levels." (PMID 34885000, 2021). "Albumin, which not only expands intravascular volume and improves microcirculation but also binds numerous substances, such as bile acids, nitric oxide, and cytokines, has been widely employed for management of cirrhosis and portal hypertension related complications in real-world clinical practice." (PMID 31596729, 2019). "It has been proposed that the effect of albumin infusion for hyponatremia in cirrhosis may be attributed to the correction of an impaired Gibbs-Donnan equilibrium that results in the imbalance of charged particles near the semipermeable membrane can alter fluid dynamics." (PMID 31596729, 2019). "Studies have shown that in patients with cirrhosis albumin is subjected to posttranscriptional modifications leading to oxidized forms of albumin with impairment of its non-oncotic biological properties and thus leading to decreased “effective” albumin concentration." (PMID 30155448, 2018). "In the multivariate analysis, serum albumin and Child-Pugh score were the baseline variables that better predicted death in patients with decompensated cirrhosis; these findings are consistent with those of a systematic review of predictors of death in patients with cirrhosis." (PMID 29642845, 2018). "Given that advanced cirrhosis in patients and animals is associated with decreased SVR, it is congruent that SVR also had statistically significant associations with laboratory indicators of liver cirrhosis, including albumin, total bilirubin, INR, and platelets." (PMID 28146577, 2017). "In addition, cirrhosis and albumin were also predictive of reduced OS." (PMID 27387757, 2016). "In addition, parameters like lymphocyte basal cGMP, SNAP-induced cGMP, bilirubin and albumin, that are markers of cirrhosis in general, and some of them are parameters to assay disease severity, remarkably also correlated with the general PREP decrease in cirrhosis." (PMID 26420028, 2015). "Blood WBC, prothrombin time, LDH, serum total protein, AF WBC, serum albumin, AF albumin, AF total protein, serum total bilirubin, AST, ALT and BUN were not statically different among group A and B. Hepatitis B, 41(45%), was the most frequent cause of cirrhosis." (PMID 25289137, 2014). "Moreover, recent studies showed that IGF-1 replacement or gene transfer therapy induced cytoprotective and anti-inflammatory effects leading to improvement of hepatic fibrosis in cirrhotic rats, and IGF-1 treatment improved serum albumin levels in patients with cirrhosis." (PMID 24595361, 2014). "• Albumin administration should be considered in patients with cirrhosis and spontaneous bacterial peritonitis, but possibly also other infections; in hypooncotic patients with acute respiratory distress syndrome; and also in patients with cirrhosis and type 1 hepatorenal syndrome." (PMID 25042164, 2014). "So far, in addition to age, alcohol consumption, duration of RA, serum albumin level, obesity, and pre-existing pulmonary fibrosis, the cumulative dose and duration of MTX use have been reported as risk factors for histological fibrosis or cirrhosis in patients with RA receiving MTX." (PMID 23107811, 2012). "The CU (Chinese University)-HCC score, developed in 2010 in Hong Kong, incorporates age, albumin, bilirubin, HBV DNA levels, and cirrhosis." (PMID 41514666, 2026).